CNN1 (calponin 1)
Description:
Thin filament-associated protein that is implicated in the regulation and modulation of smooth muscle contraction. It is capable of binding to actin, calmodulin and tropomyosin. The interaction of calponin with actin inhibits the actomyosin Mg-ATPase activity (By similarity).
Synonyms: SMCC; Sm-Calp; HEL-S-14
Tractability: PROTAC: ubiquitination databases record sites on it.
Gene: Protein-coding gene on chromosome 19 (11,538,767 to 11,550,323, forward strand). Ensembl gene ENSG00000130176.
Subcellular location (Human Protein Atlas): Actin filaments
Pathways (Reactome):
Developmental Biology: Developmental Lineage of Mammary Gland Myoepithelial Cells
Gene Ontology:
Molecular function: protein binding; actin filament binding; actin binding
Biological process: negative regulation of vascular associated smooth muscle cell proliferation; actin filament organization; regulation of smooth muscle contraction; actomyosin structure organization
Cellular component: cytoskeleton; focal adhesion; actin cytoskeleton
Genetic constraint (gnomAD): Loss-of-function variants: 21 observed, 37.29 expected, observed/expected ratio (o/e) 0.56, 90% interval 0.4 to 0.81. The upper end of that interval is the gene's LOEUF score, 0.81, which puts it in group 3 of 6, group 1 being the genes least tolerant of losing a copy. Missense variants: 314 observed, 411.47 expected, observed/expected ratio (o/e) 0.76, 90% interval 0.69 to 0.84. Synonymous variants: 164 observed, 169.59 expected, observed/expected ratio (o/e) 0.97, 90% interval 0.85 to 1.1.
Homologues: Orthologues: macaque CNN1 (99% identical), mouse Cnn1 (98% identical), rat Cnn1 (96% identical), chimpanzee CNN1 (94% identical), dog CNN1 (93% identical), guinea pig CNN1 (84% identical), pig CNN1 (82% identical), tropical clawed frog cnn1 (74% identical), zebrafish cnn1b (72% identical), zebrafish cnn1a (59% identical), Drosophila melanogaster Chd64 (24% identical), Caenorhabditis elegans cpn-2 (23% identical), and 4 more. Paralogues in human: CNN3 (68% identical), CNN2 (62% identical), TAGLN2 (29% identical), TAGLN3 (29% identical), TAGLN (27% identical).
Diseases named in the same sentence as CNN1 in open-access papers:
CNN1 is named in the same sentence as 66 diseases in open-access papers, as found by Europe PMC text mining. Sharing a sentence is not in itself a finding about the gene and the disease. The quoted sentences say what the papers report.
breast carcinoma (11 papers, 2017 to 2024). "CNN1 is downregulated and has been shown to be a tumour suppressor gene in breast cancer, inhibiting cell proliferation and invasion, and enhancing cell apoptosis." (PMID 38240701, 2024). "The differential expression of lncRNA MEG3, miRNA-330 and CNN1 was first validated in breast cancer tissues and cells." (PMID 38240701, 2024). "Several studies have identified CNN1 as a tumor suppressor, noting its decreased expression in various cancers, such as ovarian cancer, hepatocellular carcinoma, breast cancer, and colorectal cancer (CRC)." (PMID 39284282, 2024). "Overexpression of CNN1 in breast cancer cells inhibited cell survival, migration, invasion, and enhanced apoptosis." (PMID 35887085, 2022). "For example, miR-106b-5p promotes the lung metastasis of breast cancer by decreasing Calponin 1 (CNN1)." (PMID 35365168, 2022). "There is consistent evidence that miR-106-5p can promote lung metastasis of breast cancer by targeting calponin 1 (CNN1), which enhances apoptosis rate and inactivates Rho-associated coiled-coil containing protein kinase 1 (ROCK1) in breast cancer cells." (PMID 33435156, 2021). "The overexpression and knockdown of Calponin 1 (CNN1) in breast cancer cell lines were performed to conduct cell viability, migrating, invasion, proliferation, adhesion, and apoptosis experiments." (PMID 31986487, 2020). "Then we found that the expression level of CNN1 in BRCA tissues (n=20) was reduced by 50%, and the protein level of CNN1 in breast cancer cells was also downregulated, especially in MCF-7 cell line and MDA-MB-231 cell line." (PMID 31986487, 2020). "The MEG3/miR-330/CNN1 axis provides a novel insight into the pathogenesis of breast cancer and may represent candidate therapeutic targets." (PMID 38240701, 2024). "CNN1 downregulation in breast cancer cells was also observed in our study." (PMID 38240701, 2024). "The prognostic value of CNN1 in breast cancer has also been reported." (PMID 38240701, 2024). "Moreover, miR-330 mimics on the basis of lncRNA MEG3 overexpression ameliorated the tumor-suppressing effects of lncRNA MEG3 in breast cancer malignant properties by decreasing CNN1 expression." (PMID 38240701, 2024). "Conversely, inhibiting the expression of CNN1 can promote breast cancer metastasis." (PMID 37373013, 2023). "Meanwhile, the CNN1 at the late stage of breast cancer was significantly decreased." (PMID 31986487, 2020). "Besides, the miR-106b-5p mimic enhanced breast cancer canceration by targeting CNN1 and activating Rho/ROCK1 signaling pathway." (PMID 31986487, 2020). "Cellular experiments proved that CNN1 overexpression suppressed breast cancer cell cancerization." (PMID 31986487, 2020). "Rho/ROCK1 pathway inhibitor effectively alleviated the role of CNN1 in BRCA cell proliferation and invasion, indicating that miR-106b-5p could promote breast cancer cell cancerization by targeting CNN1 and Rho/ROCK1 pathway." (PMID 31986487, 2020). "However, by suppressing CNN1, metastasis in breast cancer is promoted." (PMID 37153789, 2023). "Therefore, we speculated that CNN1 overexpression might inhibit the metastasis of breast cancer by suppressing Rho/ROCK1 pathway." (PMID 31986487, 2020). "We constructed a ceRNA network comprising lncRNA MEG3, miR-330, and CNN1, implying that MEG3 plays a ceRNA role in regulating CNN1 by sponging miR-330 in breast cancer." (PMID 38240701, 2024). "Cell experiments showed consistent results that MEG3 (P < 0.01) and CNN1 expression levels (P < 0.05) were markedly decreased in human breast cancer cells MCF-7, BT-474, and MDA-MB-468 compared to those in non-cancerous human breast epithelial cells MCF10A." (PMID 38240701, 2024). "In this research, the apoptosis induced by CNN1 was confirmed by phosphatidylserine externalization in K-562 (p < 0.001) and FEPS (p < 0.001) cell lines, similar findings were reported on in vitro models of breast cancer, lung adenocarcinoma, and colon carcinoma." (PMID 35897681, 2022).
atherosclerosis (10 papers, 2011 to 2025). A disease characterized by the build-up of fatty material and calcium deposition in the arterial wall resulting in partial or complete occlusion of the arterial lumen. "An unannotated disease-specific cell cluster (A-cluster 6) co-expressed contractile VSMC markers (Myh11, Acta2, and Cnn1) with several atherosclerosis-induced ECM genes (Col1a1, Mgp, Eln, Fn1, Col4a1, and Col8a1) and had reduced levels of Ly6a, Vcam1, and Tnfrsf11b compared to imVSMCs." (PMID 40577585, 2025). "We examined whether O. scatoligenes-derived skatole promotes atherosclerosis in a CNN1-dependent manner." (PMID 41128819, 2025). "Next, we used delong test to detect whether there were statistical differences in ROC curves between CNN1 and other hub genes, and the results showed that most hub genes were significantly different from CNN1(p < 0.05), suggesting that CNN1 might be a biomarkers of atherosclerosis." (PMID 37963970, 2023). "Such low AKAP12 expression correlates with reductions in CNN1, a SMC differentiation marker known to be reduced in atherosclerosis." (PMID 21483686, 2011). "Phenotypic modulation of SMCs during human atherosclerosis is characterized by the downregulation of contractile SMC marker genes such as MYH11, TAGLN and CNN1, and activation of gene programs that promote vascular remodeling, lesion development and fibrous cap formation." (PMID 41107595, 2025). "Nevertheless, neither of these atherosclerosis-relevant in vitro conditions were able to induce Glp1r expression, even when ECs were expressing high levels of smooth muscle markers Acta2 and Cnn1." (PMID 35401813, 2022).
bladder cancer (9 papers, 2017 to 2023). "For instance, bioinformatics analysis suggests that CNN1 can be a potential bladder cancer biomarker and therapeutic target." (PMID 37373013, 2023). "It has been reported that CNN1 is lowly expressed in bladder cancer, liver cancer, and lung squamous cell carcinoma, which were associated with decreased overall survival." (PMID 37251946, 2023). "Finally, overexpression of CNN1 has been shown to inhibit the proliferation, invasion and metastasis of bladder cancer cells." (PMID 38144520, 2023). "Furthermore, our results showed that the expression of CNN1 positively correlated with poor prognosis in all 10 types of cancer, including bladder carcinoma." (PMID 37153789, 2023). "Also, CNN1, TAGLN, and TMP2 were already characterized as prognostic molecular markers for bladder cancer with higher expression associated with lower survival." (PMID 34261540, 2021). "Besides, some screened hub genes were common, like CNN1, an actin filament-associated regulatory protein expressed in smooth muscle and many types of non-muscle cells, and CCDC 34, involved in bladder carcinoma pathogenesis and non-small-cell lung cancer." (PMID 29255427, 2017). "Consistent with our study, previous studies have reported these key genes (TAGLN, CNN1, ACTC1, LMOD1) play important roles in bladder cancer." (PMID 38144520, 2023).
colorectal cancer (7 papers, 2020 to 2024). A primary or metastatic malignant neoplasm that affects the colon or rectum. "More interestingly, most recent studies based on single-cell gene expression analysis in colorectal cancer surgical specimens, concur in the identification of both CNN1 and TPM2 as TASC markers associated with poor prognosis." (PMID 35454931, 2022). "CNN1 knockdown increases the growth rate, volume, and weight of tumors while accelerating proliferation and angiogenesis in colorectal cancer." (PMID 37251946, 2023). "LINC00337 recruits DNMT1 to the promoter of the tumor-suppressive gene, CNN1 (calponin 1), to repress its expression in colorectal cancers, which further promotes VEGF-mediated tumor angiogenesis." (PMID 36010595, 2022). "The expression of CNN1 gene had previously been associated with malignant transformation and has recently been included, together with TPM2 gene expression, in a transcriptional regulatory network associated with colorectal cancer recurrence." (PMID 35454931, 2022). "Indeed, a high CNN1 expression was related to poor prognosis in colorectal cancer." (PMID 37153789, 2023). "In colorectal cancer, the knockdown of LINC00337 inhibited angiogenesis and proliferation of CRC cells because LINC00337 inhibited CNN1 expression by recruiting DNMT1." (PMID 37781524, 2023).
gastric cancer (7 papers, 2020 to 2025). A primary or metastatic malignant neoplasm involving the stomach. "Also, it was recently found that high CNN1 expression mediated the development of chemoresistance by inducing cancer-associated fibroblasts-mediated matrix stiffness in gastric cancer." (PMID 37153789, 2023). "There is a relationship between CNN1 and tumor-infiltrating lymphocytes (TILs), and the marker genes NRP1 and TNFRSF14 of TILs are significantly related to CNN1 expression in gastric cancers." (PMID 37153789, 2023). "Research has indicated that CNN1 can heighten the level of matrix stiffness facilitated by CAFs, leading to chemoresistance in gastric cancer." (PMID 37605453, 2023). "In addition to collagen, CAFs contribute to gastric cancer resistance to 5-Fluorouracil (5-Fu) by secreting myosin light chain 1 (CNN1)." (PMID 40211368, 2025). "When the eight characteristic genes (ENTPD3, PDZD4, CNN1, GTPBP4, FPGS, UTP25, CENPW, and FAM111A) are all fitted into one variable, the AUC of the ROC curve is 0.996, indicating a good diagnostic efficiency for gastric cancer." (PMID 37007099, 2023). "We have established the early diagnosis model of eight characteristic genes (ENTPD3, PDZD4, CNN1, GTPBP4, FPGS, UTP25, CENPW, and FAM111A) for gastric cancer." (PMID 37007099, 2023). "We used Cox regression analysis to investigate the association between pathological characteristics, clinical prognosis, and CNN1 and VEGF expressions in patients with gastric cancer." (PMID 37153789, 2023). "Calponin 1 elevated matrix stiffness in CAF and enhance 5-Fu chemoresistance by activation of YAP in gastric cancer." (PMID 36733484, 2023). "Mechanically, CNN1 interacts with PDLIM7 to prevent its degradation through NEDD4-1, which activates the ROCK1/MLC pathway, leading to increased matrix stiffness and enhancing 5-Fu resistance in gastric cancer cells via YAP activation." (PMID 40211368, 2025). "The expressions of CNN1 and VEGF in gastric cancer were confirmed using immunohistochemistry." (PMID 37153789, 2023). "Based on the median values of CNN1 and VEGF expressions, we separated patients into high- and low-expression groups and evaluated the correlation between CNN1 and VEGF expressions in tumor and para-cancer tissues from clinical gastric cancer patients and also various clinical characteristics." (PMID 37153789, 2023).
ovarian carcinoma (6 papers, 2013 to 2024). A malignant neoplasm originating from the surface ovarian epithelium. "Upregulation of CNN1 in these cells prevents the invasion of cancer cells to a high degree and suppresses ovarian cancer development." (PMID 35805203, 2022). "In the intraperitoneal spreading model of ovarian cancer, CNN1 acts as a suppressor in both ovarian cancer cells and peritoneal mesothelial cells." (PMID 28977852, 2017). "For instance, it has been reported that CNN1 expression could suppress ovarian cancer development." (PMID 32127961, 2020). "Overexpression of CNN1 in the non-HGSC ovarian cancer cell SKOV3 also showed similar results of suppression of migration, invasion, AIG, and subcutaneous xenograft tumorigenesis." (PMID 28977852, 2017).
fibrosarcoma (4 papers, 2017 to 2022). A malignant mesenchymal fibroblastic neoplasm affecting the soft tissue and bone. "CNN1 also exerts a tumor suppressor function in mesenchyme tumors such as leiomyosarcoma and fibrosarcoma." (PMID 28977852, 2017). "Moreover, in a fibrosarcoma cell line, the vector-induced increased expression of calponin 1 correlated with decreased motility and increased substrate adhesion." (PMID 31569405, 2019).
hepatocellular carcinoma (4 papers, 2020 to 2024). A malignant tumor that arises from hepatocytes. "In hepatocellular carcinoma cells, CNN1 was a cancer inhibitor gene that turned into a marker of cell migration." (PMID 35903683, 2022). "In vitro, CNN1 was a tumor suppressor gene that became an indicator of cell migration in hepatocellular carcinoma cells." (PMID 31986487, 2020). "Similar to the effect of CNN1 on hepatocellular carcinoma cells, CNN1 expression was downregulated and also played a negative role in uterine leiomyosarcoma." (PMID 31986487, 2020). "Both positive and negative expressions of CNN1 in tumor vascular smooth muscle have been reported, where CNN1 expression is reduced in the early stages of hepatocellular carcinoma, which is in agreement with the observations in this research." (PMID 37153789, 2023).
Hypertension (4 papers, 2020 to 2024). The presence of chronic increased pressure in the systemic arterial system. "The antioxidant tempol, which previously was shown to decrease vascular MMP-2 activity in hypertension, prevented calponin-1 loss in 2K-1C hypertensive rats, possibly by decreasing MMP-2 S-glutathionylation." (PMID 33923477, 2021). "Finally, another mechanism that contributes to the VSMC phenotype switch in hypertension is the MMP-2-induced degradation of calponin-1, as recently shown." (PMID 33923477, 2021).
prostate carcinoma (4 papers, 2021 to 2026). A carcinoma that arises from epithelial cells of the prostate gland. "One of the top increased transcript upon CASC10 knockdown was calponin-1 (CNN1) which encode a filament-associated protein with pivotal roles in cell metastasis, embryonic development, and prostate cancer progression." (PMID 35887085, 2022). "Upregulation of SPP1 and downregulation of CHRDL1 and CNN1 (genes involved in bone biology) in metastasis from all sites analyzed are found which suggests they are changed early on and could belong to the genes that make prostate cancer metastatic cells bone-gravitating." (PMID 34209195, 2021).
aneurysm (3 papers, 2022 to 2024). Bulging or ballooning in an area of an artery secondary to arterial wall weakening. "Comparing smooth muscle cell markers such as Acta2, Tagln, Myl9, Myl6, Cnn1, and Myh11, these markers were expressed less in thoracic aneurysm SMCs, suggesting a less-differentiated state of the thoracic aneurysm SMCs." (PMID 39590192, 2024). "The otherwise reduced expression level of the marker genes of contractile VSMCs (including Myocd, Srf, Myh11, Cnn1, Cnn2, and Tagln) in aneurysms was rescued in FAM3A-overexpressing aortas." (PMID 37660071, 2023).
dilated cardiomyopathy (3 papers, 2022). Cardiomyopathy which is characterized by dilation and contractile dysfunction of the left and right ventricles. "CNN1 suppresses dilated cardiomyopathy progression in mice via εPKC signaling." (PMID 35300115, 2022). "In contrast, basic studies found that CNN1 plays an essential role in DCM ventricular remodeling and can inhibit the progression of dilated cardiomyopathy in mice through εPKC signaling." (PMID 36704339, 2022).
heart failure (3 papers, 2022 to 2023). Inability of the heart to pump blood at an adequate rate to meet tissue metabolic requirements. "A study of human heart failure gene expression has shown downregulation of CNN1 expression in heart failure, which is consistent with our findings." (PMID 36704339, 2022). "We screened for differentially expressed genes in heart failure using available gene expression data from the Gene Expression Omnibus database and identified 6 important genes by a random forest classifier (ASPN, MXRA5, LUM, GLUL, CNN1, and SERPINA3)." (PMID 36254001, 2022).
lung squamous cell carcinoma (3 papers, 2022 to 2023). "Some studies have shown that CNN1 has an inhibitory effect on the malignant biological behavior of lung squamous cell carcinomas, such as invasion and migration, and also affects their epithelial–mesenchymal transition." (PMID 37153789, 2023). "It was demonstrated that CNN1 suppressed lung squamous cell carcinoma cell invasion and migration." (PMID 35903683, 2022).
aortic aneurysm (2 papers, 2021 to 2022). A ruptured aneurysm located in the wall of the proximal portion of the descending aorta proceeding from the arch of the aorta. "Decreases in α-SMA, MYH11, SM22, and CNN1 attenuate HAoSMCs contractility unit formation and further disrupt force generation, promoting the development of aortic aneurysm or dissections." (PMID 34486519, 2021).
colon carcinoma (2 papers, 2022). "In conclusion, our data strongly support the notion of a key role of TASCs in colon cancer clinical course and identify TPM2 and CNN1 as novel and robust prognostic markers for colon cancer prognostication." (PMID 35454931, 2022). "In addition, considering the functional specificities of CNN1 and TPM2 proteins, our data suggests that TASC biomechanical properties might be of relevance for colon cancer progression." (PMID 35454931, 2022).
infertile (2 papers, 2018 to 2021). "Previously, a decline of peritubular cell CNN1 was shown in infertile patients, which went hand in hand with a partial loss of other contractility proteins of peritubular cells and indicated loss of the smooth muscle phenotype, in general." (PMID 34074003, 2021). "Hence, ATP-mediated ACTA2 and CNN1 decreases in HTPCs could be first steps en route to infertility." (PMID 29362497, 2018).
lymph node metastasis (2 papers, 2020 to 2023). "Similarly, a significant difference of CNN1 expression between N0 and N1-N3 was observed for lymph node metastasis (0.73 vs. 0.41)." (PMID 31986487, 2020).